TBX21 (T-box transcription factor 21)
Diseases named in the same sentence as TBX21 in open-access papers (continued):
Sharing a sentence is not in itself a finding about the gene and the disease.
TBX21 also shares sentences with these, for which no sentence is quoted: allergic asthma (5 papers); tuberculosis (5); alveolitis (3); lung adenocarcinoma (3); ankylosing spondylitis (2); atherosclerosis (2); depression (2); dermatitis (2); graft versus host disease (2); Granuloma (2); immune deficiency (2); immune diseases (2); infectious disease (2); inflammatory bowel disease (2); neurodegenerative disease (2); Salmonella Infections (2); acute lymphoblastic leukemia (1); Allergy (1); anaplastic carcinoma (1); angioimmunoblastic T-cell lymphoma (1); Behcet disease (1); bladder cancers (1); Bone Marrow Failure (1); childhood asthma (1); chronic asthma (1); chronic sinusitis (1); colon adenocarcinoma (1); common variable immunodeficiency (1); cystic fibrosis (1); eczema (1).
A further 49 diseases each share a sentence with TBX21 in 1 paper.